BCL2 (BCL2 apoptosis regulator)
Diseases named in the same sentence as BCL2 in open-access papers (continued):
Sharing a sentence is not in itself a finding about the gene and the disease.
acute myeloid leukemia (continued). "Venetoclax, a selective Bcl-2 inhibitor, has been approved by the FDA to treat certain cancers, including chronic lymphocytic and acute myeloid leukemia." (PMID 40076649, 2025). "It is noteworthy that ABT-199 (Venetoclax), another BCL2 inhibitor targeting the BH3 domain and disrupting the BCL2/BAX interaction, has demonstrated synergy with other drugs in Acute Myeloid Leukaemia (AML)." (PMID 38928195, 2024). "Treatment with the BCL2 inhibitor venetoclax in combination with a hypomethylating agent (azacitidine or decitabine) in elderly and unfit acute myeloid leukemia (AML) patients leads to high remission rates and significantly extends overall survival over the previously available treatment regimens." (PMID 39414773, 2024). "Along with Bcl-2, other anti-apoptotic proteins, such as Mcl1 and Bcl-xL, play a critical role in the survival of cancer cells in other hematological malignancies, such as acute myeloid leukemia (AML) and multiple myeloma (MM)." (PMID 39684550, 2024). "The standard-of-care treatment for patients with acute myeloid leukemia (AML) is being challenged by new classes of targeted therapies, including FLT3, IDH and BCL2 inhibitors." (PMID 38783160, 2024). "The expression of METTL3 has been shown to be increased in acute myeloid leukemia (AML) patients, suppressing cell differentiation and apoptosis, and promoting cell proliferation through increased translation of c-MYC, BCL2, and PTEN." (PMID 39457524, 2024). "It is the first and only FDA-approved BCL-2 inhibitor to treat chronic lymphoytic leukemia (CLL) and some types of acute myeloid leukemia (AML)." (PMID 39906657, 2024). "At present, Venetoclax, the first highly selective BCL-2 inhibitor, has been approved by the Food and Drug Administration (FDA) for the treatment of chronic lymphocytic leukemia (CLL) and acute myeloid leukemia (AML)." (PMID 39060763, 2024). "BH3-mimetic agents that directly trigger apoptosis in cancer cells reliant on BCL-2 or its pro-survival relatives have emerged as powerful agents for treating chronic lymphocytic leukemia (CLL) and acute myeloid leukemia (AML)." (PMID 39052583, 2024). "Progressing myelodysplastic syndrome (MDS) into acute myeloid leukemia (AML) is an indication for hypomethylating therapy (HMA, 5-Azacytidine (AZA)) and a BCL2 inhibitor (Venetoclax, VEN) for intensive chemotherapy ineligible patients." (PMID 39839764, 2024). "Moreover, alkaliptosis is also a promising strategy in drug-resistant cancers like acute myeloid leukemia (AML), where alkaliptosis overcomes BCL-2-mediated resistance." (PMID 39768186, 2024). "The standard treatment for elderly patients with acute myeloid leukemia (AML) is venetoclax (Ven), a BCL-2–selective inhibitor, combined with hypomethylating agents (HMA) such as azacitidine or decitabine." (PMID 36860654, 2023). "With dysregulation of apoptosis mechanisms being essential components of leukemia development, progression, and therapy resistance, discovery of the BCL-2 inhibitor venetoclax transformed the therapeutic landscape of acute myeloid leukemia (AML) as well as that of chronic lymphocytic leukemia (CLL)." (PMID 37190037, 2023). "Studies demonstrating increased expression of BCL-2 in Leukemia stem cells and its ability to induce differential apoptosis compared to HSC with inhibition of BCL-2 in Acute Myeloid Leukemia led to further studies that evaluated different BCL-2 inhibitors in AML." (PMID 37296964, 2023). "Venetoclax, an inhibitor of the antiapoptotic protein Bcl-2, has been approved for CLL and acute myeloid leukaemia (AML) and clinically confirmed to be efficient for B-ALL." (PMID 36091028, 2022). "The DNA hypomethylating agent azacytidine, in combination with the BCL-2 inhibitor venetoclax, suppresses Complex II activity by reducing sdhA glutathionylation, which inhibits OXPHOS activity in acute myeloid leukemia stem cells (AML LSCs)." (PMID 36612059, 2022).
acute myeloid leukemia (continued). "Next, we tested the effects of antiapoptotic Bcl-2 family proteins BCL-2 and BCL-xL on TR-induced cell death, using human acute myeloid leukemia HL60 cells ectopically expressing BCL-2 or BCL-xL." (PMID 36294912, 2022). "Remarkably, 6 showed a significantly improved anti-tumorefficacy in a Kasumi-1 acute myeloid leukemia (AML) cell line, whichcritically depends on both BCL-xL and BCL-2 for survival." (PMID 35816671, 2022). "It was found that METTL3 and METTL14 (writers) served an oncogenic role in acute myeloid leukemia (AML) in an m6A manner by promoting the translation of MYC, MYB, BCL2, SP1, and PTEN." (PMID 36281789, 2022). "Venetoclax, a BCL-2 inhibitor, has been proven to be highly effective in both CLL and acute myeloid leukemia (AML) and has been approved for the treatment of both diseases." (PMID 35193595, 2022). "For example, in acute myeloid leukemia (AML), overexpressed METTL3 promotes cell proliferation and inhibits cell differentiation by modifying c-MYC, BCL-2, and PTEN with m6A." (PMID 36293529, 2022). "Venetoclax, a specific BCL-2 inhibitor, is a first-in-class BH3-mimetic that is FDA approved in both CLL and acute myeloid leukaemia (AML)." (PMID 34442359, 2021). "Co-expression of BCL2 and MCL1 has been reported in NHLs and MCL1 dependency is also seen in acute myelogenous leukemia and multiple myeloma." (PMID 33670870, 2021). "All the tested compounds (4, 5a–l) were found to inhibit the growth of the Bcl-2-expressing human cancer cell lines (MDA-MB-231, HeLa and KG1a) with low micromolar IC50 values, except 5c, which was inactive against the KG1A (Acute Myeloid Leukemia) cell line." (PMID 34830153, 2021). "The FDA recently approved eight targeted therapies for acute myeloid leukemia (AML), including the BCL-2 inhibitor venetoclax." (PMID 34302041, 2021). "GBPs induce caspase-dependent apoptosis in chronic myeloid leukemia (CML) and acute myeloid leukemia (AML) cells, where the proapoptotic BCL-2 member, BAK, is an indispensable mediator." (PMID 34294680, 2021). "Venetoclax, a specific BCL-2 inhibitor, was FDA-approved in combination with hypomethylating agents for the treatment of acute myeloid leukemia (AML) in adults." (PMID 34633564, 2021). "methanolic leaf extract showed a promising selective anti-proliferative and pro-apoptotic effect on acute myeloid leukemia cell lines, by cleaving PARP, releasing cytochrome-c, and increasing the Bax/Bcl-2 ratio." (PMID 32069824, 2020). "Compound 4j (and several other examples) possessed low- to sub-micromolar IC50 values against Bcl-2 expressing human cancer cell lines such as MDA-MB-231 (invasive breast), HeLa (cervical) and KG1a (acute myelogenous leukemia)." (PMID 33256166, 2020). "Given the high volume of information about the relevance of Bcl-2 inhibitors in hematologic malignancies, including acute myeloid leukemia (AML), mature B-Cell malignancies and lymphoid malignancies, this article will focus mainly on Bcl-2 inhibitor application in solid tumors." (PMID 32455818, 2020). "Finally, Skd3 has also emerged as a factor in Venetoclax resistance, a FDA-approved drug for the treatment of acute myeloid leukemia (AML), which exerts its mechanism via BCL-2 inhibition." (PMID 32573439, 2020). "The depletion of m6A methyltransferase METTL3 reduces the translation efficiency of genes with m6A modification, such as c-MYC, BCL2 and PTEN, and promotes cell differentiation in acute myeloid leukemia." (PMID 30212448, 2018). "Venetoclax, a small molecule BH3 mimetic which inhibits the anti-apoptotic protein Bcl-2, and idasanutlin, a selective MDM2 antagonist, have both shown activity as single-agent treatments in pre-clinical and clinical studies in acute myeloid leukemia (AML)." (PMID 27353420, 2016). "Sorafenib, a potent multikinase inhibitor, induces apoptosis of human acute myeloid leukemia (AML) cells through downregulating Mcl-1 and enhancing binding of Bim to Bcl-2 and Bcl-xL." (PMID 26405162, 2015).
acute myeloid leukemia (continued). "Recently, the differential compartmentalization of Bcl2 and NRAS has been reported to influence disease states, such as myelodysplastic syndromes and acute myeloid leukemia." (PMID 22069448, 2011). "In addition, relative to parental venetoclax, two of our lead compounds, BD‐4‐213 and AMC‐4‐154, exhibited superior activities against the acute myeloid leukemia cell line MV4;11 and an MV4;11 cell line engineered to overexpress BCL‐2." (PMID 40370107, 2025). "Over the past decade, treatment strategies for acute myeloid leukemia (AML) have undergone substantial transformation, with a growing emphasis on combining targeted agents, such as BCL-2, FLT3, and IDH inhibitors, with conventional chemotherapy to enhance patient outcomes." (PMID 41294812, 2025). "An example of an approved therapy is Venetoclax, a BCL2 inhibitor which has demonstrated efficacy as a monotherapy or in combination regimens for treating chronic lymphocytic leukemia (CLL), small lymphocytic lymphoma (SLL), and acute myeloid leukemia (AML)." (PMID 39184045, 2024). "Although myelodysplastic syndrome (MDS) during progression to acute myeloid leukemia (AML) is indicated for hypomethylating therapy (HMA, 5-Azacytidine (AZA)), the addition of a BCL2 inhibitor (Venetoclax, VEN) yields significantly better responses in patients unsuitable for intensive chemotherapy." (PMID 39839764, 2024). "In acute myeloid leukemia (AML), primary cancer cells that were resistant to cytarabine (AraC) and had a high “MitoScore,” which identified cells with high reliance on oxphos, were highly reliant on B cell lymphoma-2 (BCL-2) expression." (PMID 37779896, 2023). "Preclinical data on simultaneous BCL-2 and PI3K inhibition in Richter’s syndrome, diffuse large B-cell lymphoma (DLBCL), and acute myeloid leukemia (AML) support the hypothesis of synergistic effects of this combinatorial approach." (PMID 36674872, 2023). "Together, these data indicated that high-UNC93B1 expressed AML cells shows greater dependence on MCL1 than BCL2 for survival, and UNC93B1 might be a biomarker to predicting drug response in acute myeloid leukemia." (PMID 36741319, 2023). "We analyzed the expression of BCL2, BAX, and ABCB1 in bone-marrow samples collected at diagnosis from 51 adult patients with acute myeloid leukemia with normal karyotype (AML-NK) using real-time polymerase chain reaction method, and examined their prognostic potential." (PMID 37078709, 2023). "Likewise, RSV chemosensitization to DOX is mediated by inhibition of MDR1/P-gp and Bcl-2 in ovarian cancer cells (OVCAR-3), acute myeloid leukemia (AML-2) and oral squamous cell carcinoma (KBv200)." (PMID 38026933, 2023). "Studies have shown that the combination of ST1326 and ABT199 (Bcl-2 inhibitor) can enhance the anti-acute myeloid leukemia (AML) effect of the latter, indicating that cpt1a may become a potential drug target for the treatment of AML." (PMID 36588702, 2022). "The Bcl-2 inhibitor Venetoclax promotes CLL cell apoptosis, and induces rapid and pronounced activation and mitochondrial translocation of Bax in cell lines of acute myeloid leukemia." (PMID 35392232, 2022). "In addition to navitoclax, a recent study has described a novel dual BCL-2/BCL-XL inhibitor AZD4320, which appears to be highly active in acute myeloid leukemia (AML) preclinical models with reduced thrombocytopenia." (PMID 33799470, 2021). "Of those genes, BCL2 and PTGS2 were shown to be upregulated in acute myeloid leukemia." (PMID 34422220, 2021).
acute myeloid leukemia (continued). "CD200 and BCL2 overexpression is independently associated with inferior survival in acute myeloid leukemia (AML), and these two factors are frequently co-expressed; however, no data are available on the role of concomitant aberrant CD200 and BCL2 expression on outcome of AML patients." (PMID 33596632, 2021). "Further analysis within the non-adherent leukemic cell lines KG1a (acute myelogenous leukemia, Bcl-2 +ve) and Jurkat (T-cell leukemia, Bcl-2 −ve,) was carried out by using the CellTiter-Blue® assay according to published precedent." (PMID 33256166, 2020). "In acute myelogenous leukemia (AML), METTL3 controls myeloid differentiation of normal hematopoietic and leukemia cells by promoting m6A-mediated translation of apoptotic genes such as C-MYC, BCL-2, and PTEN." (PMID 33552994, 2020). "The combination of S63845 with venetoclax, which is a FDA-approved BCL-2 inhibitor, has potent activity against nasopharyngeal carcinoma, acute myeloid leukemia, and mantle cell lymphoma without severe toxicity." (PMID 32152266, 2020). "On the contrary, the highly selective Bcl2 inhibitor Venetoclax presented remarkable cytotoxic effects with significant reduced toxicity in comparison to dual Bcl2/Bcl-X inhibitors in haematological malignancies, including acute myeloid leukemia (AML) and non-Hodgkin lymphoma (NHL)." (PMID 33255367, 2020). "For example, the m6A methyltransferases METTL3/14 and WTAP could act as oncogenic factors by promoting the translation of several oncogenes including c-MYC, BCL2, PTEN, and mTOR in acute myeloid leukemia." (PMID 33584787, 2020). "Moreover, combining BH3-mimetics to target both BCL-2 and MCL1 had potent activity in pre-clinical models of acute myeloid leukemia and in T-cell acute lymphoblastic leukemia cells." (PMID 31718075, 2019). "Other events such as the overexpression of Bcl-2 or a mutated and activated form of Kras are required to provoke an MPN like disease that can progress to acute myeloid leukemia (AML) in the absence of Gfi1." (PMID 29925903, 2019). "Cotreatment with the Brd4 inhibitor JQ1 and the HDAC inhibitor panobinostat synergistically induced apoptosis of human acute myelogenous leukemia (AML) blast progenitor cells (BPC) through attenuation of c-Myc and Bcl-2 expression, while increasing p21 and Bim expression." (PMID 26405162, 2015). "For instance, in acute myeloid leukemia (AML), increased m6 A levels on SP1, MYB, MYC, BCL2, and PTEN enhance the stability and translation of their corresponding mRNAs, contributing to the onset and progression of AML." (PMID 40382536, 2025). "Elevated BCL2 levels are also seen in chronic lymphocytic leukemia (CLL), diffuse large B-cell lymphoma (DLBCL), and acute myeloid leukemia (AML), contributing to poor treatment response." (PMID 41155156, 2025). "The selective inhibitor of BCL2, ABT199 (venetoclax), has been approved for the treatment of chronic lymphocytic leukemia (CLL) and acute myeloid leukemia (AML), highlighting the potential of this targeted treatment therapy." (PMID 38622118, 2024). "The combination of the BCL2 inhibitor venetoclax (VEN) and azacitidine (AZA) has changed the paradigm of treatment for elderly or unfit acute myeloid leukemia (AML) patients." (PMID 38539426, 2024). "BH3 mimetic antagonists to BCL-2 and MCL-1 has been considered as an anti-tumor strategy to induce cell death in acute myeloid leukemia (AML), and resistance to BH3 mimetics has been identified as a critical clinical problem." (PMID 39035027, 2024). "The BCL‐2 inhibitor venetoclax (VEN) was approved in 2018 by the US Food and Drug Administration and showed excellent efficacy in acute myeloid leukemia (AML)." (PMID 39031026, 2024).
acute myeloid leukemia (continued). "CRISPR/Cas9 screening platform have been used to identify genetic vulnerabilities in acute myeloid leukemia (AML) cells, including several established (such as DOT1L, BCL2, and MEN1) and novel (such as KAT2A) therapeutic targets for AML." (PMID 39696697, 2024). "It is the first BCL-2 antagonist approved for cancer therapy, successfully used in CLL and in acute myeloid leukemia (AML)." (PMID 36968995, 2023). "VCX is a highly selective BCL2 inhibitor that is approved by the Food and Drug Administration (FDA) for the treatment of CLL and acute myeloid leukemia (AML)." (PMID 40395294, 2023). "In acute myeloid leukemia, downregulation of SDHB sensitized leukemia cancer cells to BCL-2-inhibitor-induced apoptosis, which may explain the specific anti-tumor effect of the BCL-2 inhibitors towards high OTX2-AS1 expressing cells in medulloblastoma." (PMID 37976029, 2023). "Emodin induces apoptosis and growth inhibition of AML (acute myeloid leukemia) cells through the activation of caspase-9, caspase-3, PARP (poly-ADP-ribose-polymerase), cleavage and decrease of the expression of antiapoptotic factors such as Bcl-2 (B-cell lymphoma 2)." (PMID 35011730, 2022). "For instance, Venetoclax (ABT-199), the first commercially available selective BCL-2 inhibitor, is primarily approved for treating chronic lymphocytic leukemia (CLL) and acute myeloid leukemia (AML)." (PMID 36313628, 2022). "Furthermore, the CXCR4 antagonist induces the apoptosis of acute myeloid leukemia (AML) cells, and this apoptosis is mediated by the upregulation of miR-15a/miR-16-1, which results in the downregulation of the target genes cyclin D1 and Bcl-2." (PMID 35941537, 2022). "By encouraging the translation of these mRNAs, METTL3 activity boosts and augments MYC, BCL2, and PTEN in human acute myeloid leukemia (AML)." (PMID 36551330, 2022). "For example, the depletion of METTL3 in acute myeloid leukemia (AML) cells induced cell differentiation and apoptosis through METTL3-mediated m6A modification on MYC, BCL2 and PTEN mRNA, thus delaying AML progression." (PMID 34996469, 2022). "We recently reported that 8-Cl-Ado and the BCL-2-selective inhibitor venetoclax (VEN) synergistically inhibit FAO and OXPHOS in LSCs, thereby suppressing acute myeloid leukemia (AML) growth in vitro and in vivo." (PMID 35326597, 2022). "This includes human granulosa cells, murine macrophages, and acute myeloid leukemia cells, to name a few, supporting that BPA likely induces apoptosis predominantly through the intrinsic pathway by influencing the levels of BAX to BCL-2 proteins present around the mitochondria." (PMID 36387888, 2022). "B-cell lymphoma 2 (BCL-2) and other BCL-2-like family members of proteins such as BCL-XL and MCL-1 are highly expressed in leukemia such as acute myeloid leukemia (AML) and account for treatment resistance to chemotherapeutics." (PMID 35326111, 2022). "Treatment of acute myeloid leukemia (AML) patient cells in the presence of serum with PS-ASO showed increased sensitivity to cytostatic drugs: daunorubicin or l-P-D-arabinofura-nosyl-cytosine (ara-C), thereby establishing Bcl-2 PS-ASO as more clinically relevant." (PMID 35056993, 2022). "Venetoclax is a BH3 mimetic that selectively inhibits BCL-2 and is approved for use in chronic lymphoid leukemia (CLL) and acute myeloid leukemia (AML)." (PMID 33918370, 2021). "In mice, the knockout of miRNA miR-15/16, leading to the overexpression of the pro-survival factor BCL2 as well as ROR1, induced the development of B cell lymphoma in 23% of the animals, while 77% developed an aggressive acute myeloid leukemia (AML)." (PMID 33445713, 2021). "Studies of synergism between venetoclax (ABT-199, a selective BCL-2 inhibitor) with selective inhibitors of nuclear export (SINE) yielded in vitro and in vivo promising results in acute myeloid leukemia (AML) and diffuse large-B cell lymphoma (DLBCL) models." (PMID 33413657, 2021).